IPO9 (importin 9)
Description:
Nuclear transport receptor that mediates nuclear import of proteins, such as histones, proteasome and actin. Serves as receptor for nuclear localization signals (NLS) in cargo substrates. Is thought to mediate docking of the importin/substrate complex to the nuclear pore complex (NPC) through binding to nucleoporin and the complex is subsequently translocated through the pore by an energy requiring, Ran-dependent mechanism. At the nucleoplasmic side of the NPC, Ran binds to the importin, the importin/substrate complex dissociates and importin is re-exported from the nucleus to the cytoplasm where GTP hydrolysis releases Ran. The directionality of nuclear import is thought to be conferred by an asymmetric distribution of the GTP- and GDP-bound forms of Ran between the cytoplasm and nucleus. Mediates the import of pre-assembled proteasomes into the nucleus; AKIRIN2 acts as a molecular bridge between IPO9 and the proteasome complex. Mediates the nuclear import of histones H2A, H2B, H4 and H4. In addition to nuclear import, also acts as a chaperone for histones by preventing inappropriate non-nucleosomal interactions. Mediates the nuclear import of actin (By similarity).
Synonyms: Imp9; FLJ10402
Tractability: Small molecule: a structure with a bound ligand is known. PROTAC: ubiquitination databases record sites on it; its protein half-life has been measured.
Gene: Protein-coding gene on chromosome 1 (201,829,104 to 201,884,291, forward strand). Ensembl gene ENSG00000198700.
Subcellular location: Cytoplasm; Nucleus
Subcellular location (Human Protein Atlas): Cytosol; Nucleoplasm
Gene Ontology:
Molecular function: histone binding; histone chaperone activity; nuclear import signal receptor activity; protein binding; small GTPase binding
Biological process: proteasome localization; protein import into nucleus; intracellular protein transport
Cellular component: cytoplasm; cytosol; membrane; nucleoplasm; nucleus; nuclear envelope
Genetic constraint (gnomAD): Loss-of-function variants: 21 observed, 97.61 expected, observed/expected ratio (o/e) 0.22, 90% interval 0.15 to 0.31. The upper end of that interval is the gene's LOEUF score, 0.31, which puts it in group 1 of 6, group 1 being the genes least tolerant of losing a copy. Missense variants: 785 observed, 1,094.9 expected, observed/expected ratio (o/e) 0.72, 90% interval 0.68 to 0.76. Synonymous variants: 387 observed, 412.57 expected, observed/expected ratio (o/e) 0.94, 90% interval 0.86 to 1.02.
Homologues: Orthologues: chimpanzee IPO9 (100% identical), dog IPO9 (99% identical), rabbit IPO9 (99% identical), macaque IPO9 (99% identical), rat Ipo9 (99% identical), mouse Ipo9 (99% identical), guinea pig IPO9 (98% identical), pig IPO9 (96% identical), tropical clawed frog ipo9 (86% identical), zebrafish ipo9 (85% identical), Drosophila melanogaster Ipo9 (37% identical). Paralogues in human: IPO7 (18% identical), IPO8 (16% identical), IPO11 (16% identical), CSE1L (13% identical).
Diseases named in the same sentence as IPO9 in open-access papers:
IPO9 is named in the same sentence as 7 diseases in open-access papers, as found by Europe PMC text mining. Sharing a sentence is not in itself a finding about the gene and the disease. The quoted sentences say what the papers report.
ovarian carcinoma (2 papers, 2025 to 2026). A malignant neoplasm originating from the surface ovarian epithelium. "Note of worth, four genes (IPO9, KPNA2, TNPO3, and XPOT) and one gene (KPNA5) were consistently significantly up‐ and down‐regulated in ovarian cancer, respectively." (PMID 40145330, 2025).
breast carcinoma (1 paper, 2025). "At the same time, IPO9 could control F-actin dynamics in breast cancer cells, as a cancer promoter." (PMID 40429863, 2025).
Obesity (1 paper, 2024). Accumulation of substantial excess body fat. "Research has indicated that the expression of IPO9 is regulated by m6A modification sites, which may be closely linked to the pathogenesis of obesity." (PMID 38919616, 2024).
cancer (4 papers, 2022 to 2025). A tumor composed of atypical neoplastic, often pleomorphic cells that invade other tissues. "Recent studies have suggested that RHOJ is preferentially expressed in epithelial-to-mesenchymal transition cells, with interaction with proteins (FLNB, TLN1 and IPO9) that regulate nuclear actin and inhibit actin polymerization in cancer cells." (PMID 39984455, 2025). "Importin 9 (IPO9) and 5 (IPO5) have also been implicated to play a similar role in D. melanogaster during spermatogenesis and in human cancer cells." (PMID 37767001, 2023).
tumor (3 papers, 2024 to 2026). "Further analysis identifies IPO9 as a core gene upregulated in OC, promoting tumor progression by inhibiting HMOX1‐dependent ferroptosis." (PMID 41584724, 2026). "RHOJ promotes the function of tumor-associated endothelial cells and drives EMT through its interaction with the IPO9/EpCAM signaling pathway, thereby increasing cell survival and drug resistance." (PMID 41548474, 2026).
infection (1 paper, 2020). The state of being infected such as from the introduction of a foreign agent such as serum, vaccine, antigenic substance or organism. "Infection of VSMCs with Ad:IPO9 significantly inhibited proliferation of VSMCs and significantly inhibited their migration." (PMID 32119877, 2020). "Infection of cells with Ad:IPO9 also significantly increased nuclear actin monomer levels, while infection with Ad:XPO6 or Ad:mDIA-CT significantly decrease basal nuclear actin monomer levels." (PMID 32119877, 2020).
IPO9 also shares sentences with these, for which no sentence is quoted: glioma (1 paper).